CYP1B1 (cytochrome P450 family 1 subfamily B member 1)
Diseases named in the same sentence as CYP1B1 in open-access papers (continued):
Sharing a sentence is not in itself a finding about the gene and the disease.
cancer (continued). "Specific genetic variations in CYP1A1 and CYP1B1 genes were found to be more prevalent in certain cancer patients compared with the control group, suggesting that these polymorphisms might contribute to an increased susceptibility to cancer." (PMID 39062040, 2024). "Studies have shown that five cytochrome P450 1B1 (CYP1B1) variants, which could change the hydroxylation activity of estrogen, have greater than twofold higher activity than the wild-type enzyme, thereby increasing the risk for cancers." (PMID 35664769, 2022). "Further studies into the role of CYP1B1 in BOLD-100 mediated inhibition of cancer cell proliferation will be needed to understand whether SNPs associated with this gene can affect drug sensitivity in different cancers." (PMID 32947941, 2020). "The induction of cytochrome P450 (CYP)1A1 and CYP1B1 by environmental xenobiotic chemicals or endogenous ligands through the activation of the aryl hydrocarbon receptor (AhR) has been implicated in a variety of cellular processes related to cancer, such as transformation and tumorigenesis." (PMID 31698770, 2019). "Induction of CYP1A1 and CYP1B1 by environmental xenobiotic chemicals or endogenous ligands through the activation of the aryl hydrocarbon receptor (AhR) has been implicated in a variety of cellular processes related to cancer, such as transformation and tumorigenesis." (PMID 31698770, 2019). "With some cytochrome P450s especially CYP1B1 showing increased expression in tumour cells and the tumour associated expression of individual cytochrome P450s has been exploited as therapeutic targets for P450 mediated pro-drug activation and as a cancer vaccine." (PMID 27341022, 2016). "Moreover, CYP1B1 polymorphisms have been implicated as risk factors in various cancers, and CYP1B1-mediated carcinogenesis may depend on CYP1B1 enzymatic activity." (PMID 26981862, 2016). "By searching PUBMED, we find that CYP1B1 (a member of cytochrome P450 enzyme), a differentially expressed gene annotated in this module, was reported to be associated with high risk for developing several forms of cancers, which is again consistent with our finding." (PMID 15774002, 2005). "Several studies have demonstrated differential expressions of CYP1A1 and CYP1B1 across various tumor types compared with normal tissue, suggesting their potential application in cancer prognosis and therapy." (PMID 41009721, 2025). "CYP1B1 and APOD have already been associated with tumor pathobiology in the literature, and their roles in various cancers are explored below." (PMID 40989158, 2025). "Background/Objectives: Cytochrome 1B1 (CYP1B1) is overexpressed in several cancers, contributing to carcinogenesis, cancer progression, and chemoresistance." (PMID 41155673, 2025). "Early IHC studies demonstrated the expression of CYP1B1 in neoplastic cells of multiple cancer types, leading to the suggestion that CYP1B1 is a universal cancer marker." (PMID 40478625, 2025). "Growing evidence points to a crucial role for CYP1B1 in cancer and other diseases through the impaired metabolism of endogenous compounds such as estrogens." (PMID 40807256, 2025). "Several reports have demonstrated that resveratrol inhibits the expression of many cytochrome P450 genes, including those encoding CYP1A1, CYP1B1, CYP1A2, and CYP19 in cancer cell lines of different tissue origin in humans." (PMID 40807256, 2025). "Our data indicate that CYP1B1 is also expressed in the CAAs and that it fosters AT‐dependent cancer promotion." (PMID 39806854, 2025). "Given its tumor-specific expression pattern and role in carcinogen bioactivation, CYP1B1 has emerged as a promising target for cancer chemoprevention and therapy." (PMID 40883330, 2025). "CYP1B1 is known to metabolize a wide range of xenobiotics and is often overexpressed in cancer, making it a potential biomarker for HNSCC and a target for selective inhibitors." (PMID 41174467, 2025).
cancer (continued). "Overall, our findings lay a foundation for the development of PA-based CYP1B1 inhibitors and contribute to the broader effort of harnessing dietary polyphenols in cancer prevention." (PMID 40883330, 2025). "Among the various CYP isoforms, CYP1B1 has garnered significant attention because of its distinctive expression profile and its role in cancer biology and drug resistance." (PMID 40435846, 2025). "Such involvement in tumorigenesis positions CYP1B1 as a promising target for the development of novel cancer therapies." (PMID 41155673, 2025). "The discovery of PA as a CYP1B1 inhibitor is particularly significant in the context of cancer chemoprevention." (PMID 40883330, 2025). "Among the DEGs in the three above‐mentioned pathways, ADAM12 and CYP1B1 are overexpressed in the obese group compared to the other groups and were selected for further studies due to their relevance in cancer." (PMID 39806854, 2025). "Notable upregulated genes included CYP1B1, a xenobiotic metabolizing enzyme frequently overexpressed in cancer." (PMID 40056285, 2025). "Future studies are warranted to assess the pharmacodynamic efficacy and tissue-selective effects of PA in CYP1B1-overexpressing cancer models." (PMID 40883330, 2025). "For instance, CYP1B1, which is highly expressed in many cancers, converts estradiol to 4-hydroxyestradiol, which is oxidized by peroxidases into the probable carcinogenic metabolite estradiol-3,4-quinones." (PMID 39062040, 2024). "In intestinal GC, CYP1B1 expression is inversely correlated with several cancer-related genes such as IDO1, a gene involved in the early steps of tryptophan metabolism that contributes to the endogenous AhR ligand kynurenine expression." (PMID 39200369, 2024). "CYP1B1 was the most significantly expressed form in diffuse GC, as previously reported in a wide range of human cancers including breast, colon, lung, and others, mainly in the cytoplasm in GC which is expected for an enzyme involved in xenobiotic metabolism." (PMID 39200369, 2024). "Further, our study aimed to characterize in GC how AhR and the AhR-related genes cytochrome P450 1A1 (CYP1A1) and P450 1B1 (CYP1B1) affect the mRNA expression of a panel of genes involved in cancer development and progression." (PMID 39200369, 2024). "CYP1B1 is known as a universal cancer antigen as it is expressed in almost all human cancer types but is rarely expressed in normal tissues." (PMID 39872522, 2024). "It was demonstrated that wild-type mice with CYP1B1 developed higher rates of cancer in many organs (including the ovaries) than CYP1B1-null mice following treatment with a chemical carcinogen." (PMID 38001897, 2023). "CYP1B1 was also found to enhance cancer progression through the induction of the epithelial–mesenchymal transition (EMT) and the Wnt/β-catenin pathway through Sp1 induction." (PMID 38001897, 2023). "CYP1B1 is a member of the cytochrome P450 family, it is helping cancer cells resisted the toxicity of chemical drugs by oxidation and metabolism of many anticancer drugs." (PMID 37565919, 2023). "Recently, researchers have reported that CYP1B1 plays a critical role in anti-cancer drug resistance." (PMID 37059712, 2023). "As a result of the abnormal expression in cancer, CYP1B1 has been defined as a candidate tumor antigen." (PMID 36428734, 2022). "In this study, we comprehensively investigated the clinical and immunological pattern of CYP1B1 determined from RNA-seq data across TCGA pan-cancer." (PMID 36428734, 2022). "An increased expression of CYP1B1 has been observed in some cancer cells that modify the biotransformation of paclitaxel, docetaxel, and flutamide." (PMID 36077660, 2022). "α-naphthoflavone (ANF) is a CYP1B1 inhibitor that can reduce the multidrug resistance (MDR) of cancer cells to DTX by inhibiting the expression of CYP1B1." (PMID 36091467, 2022).
cancer (continued). "CYP1B1 is a cytochrome P450 enzyme known to regulate transcription factors and allows cancer cells to reduce the toxicity of drugs by metabolizing a variety of pre-carcinogens and anticancer drugs." (PMID 36556227, 2022). "By investigating RNA-seq data from 33 cancers in the TCGA, we explored the differential expression of CYP1B1 between tumor samples and healthy samples." (PMID 36428734, 2022). "Four algorithms, including EPIC, MCPCOUNTER, XCELL, and TIDE, were used to evaluate the correlation between the CAFs and the CYP1B1 expression level in 33 cancers." (PMID 36428734, 2022). "In cancer cells and the cancer microenvironment, CYP1B1 promotes cancer development by activating xenobiotics and steroids, producing proinflammatory and angiogenic factors, and directly regulating endothelial cell angiogenesis." (PMID 35678542, 2022). "The relationship between CYP1B1 expression and clinical prognosis in 33 cancers was further analyzed." (PMID 36428734, 2022). "CYP1B1 overexpression in various types of cancer has previously been reported to modify the biotransformation of chemotherapeutics, such as mitoxantrone, flutamide (FLUT), docetaxel (TXT), and PTX." (PMID 35206262, 2022). "Our results found that CYP1B1 expression was associated with TMB, MSI, and neoantigen in pan-cancer, especially in LIHC and STAD." (PMID 36428734, 2022). "First, the clinical and immunological characteristics of CYP1B1 in cancer were based on the public database; the roles of CYP1B1 still needs to be further verified by multi-center data." (PMID 36428734, 2022). "The functional significance of CYP1B1 expression in cancer was first demonstrated in endometrial cancers." (PMID 36077068, 2022). "According to the median expression of CYP1B1, the cancers were divided into high- and low-expression groups." (PMID 36428734, 2022). "CYP1B1 is also involved in the positive regulation of inflammatory cytokine, which acts on both cancer cells and the tumor microenvironment." (PMID 36428734, 2022). "CYP1B1 is highly expressed in many cancer types and has been known as a potential target for a long time." (PMID 34556703, 2021). "This CYP1B1-based vaccine (ZYC300) activated the immune system, producing cytotoxic T lymphocytes against cancer cells expressing CYP1B1." (PMID 34636736, 2021). "Our findings showed that CYP1B1 was inhibited by quercetin, which is similar to previous research using human cancer cell lines, including THP-1, HUVECs, and human aortic endothelial cells (HAECs)." (PMID 34385920, 2021). "Accumulating data indicate that modulation of CYP1B1 can decrease adipogenesis and tumorigenesis and prevent obesity, hypertension, atherosclerosis, and cancer." (PMID 33219472, 2021). "This applies particularly to CYP1B1, where it metabolizes many xenobiotics to procarcinogens, leading to the development of many cancers." (PMID 34636736, 2021). "One of the emerging molecular changes in cancer cells is the aberrant expression of cytochrome P450 1B1 (CYP1B1)." (PMID 34636736, 2021). "These previous anti-cancer drug studies and our gemcitabine data show that the co-administration of CYP1B1 inhibitors and anti-cancer drugs decreases drug resistance and ameliorates the outcome of anti-cancer therapy." (PMID 34680513, 2021). "Of interest is the emerging research about the potential facets of aberrant CYP1B1 expression in several cancers and its promising role in anticancer drug development." (PMID 34636736, 2021). "It is well described that CYP1A1, CYP1A2, and CYP1B1 play an important role in the detoxication of environmental carcinogens and in the metabolic activation of dietary compounds with cancer preventive activity." (PMID 33219472, 2021). "The metabolic genes, CYP1A1 and CYP1A2, were widely underexpressed in multiple cancer types, whereas CYP1B1 exhibited different alterations in expression patterns." (PMID 33842355, 2021).
cancer (continued). "CYP1B1 and CYP1A1 are involved in the carcinogenic process, in which CYP1B1 mRNA and protein overexpression have been detected in a variety of malignant tumors." (PMID 34829589, 2021). "The development and progression of cancer is greatly affected by cytochrome P450 1B1 (CYP1B1) via activation of estrogens and carcinogens." (PMID 34698063, 2021). "Of importance in cardio-oncology, CYP1B1 has been shown to be expressed in cardiovascular tissues and overexpressed in malignant tumors." (PMID 33185690, 2020). "In a study done by Kwon and Chun on different cell lines, including MCF-7, MDA-MB-231, and HeLa cells, they reported that CYP1B1 increased invasion and inhibited cancer cell apoptosis." (PMID 32626511, 2020). "For instance, in 2015, Li and colleagues conducted a meta-analysis to carry a comprehensive and quantitative analysis on the role of CYP1B1 in cancer." (PMID 33185690, 2020). "Another way in which CYP1B1 has been shown to play a role in cancer development is by enhancing the invasion of MCF-7 and MCF-10A cells." (PMID 33185690, 2020). "Several chemotherapeutic agents have been shown to induce CYP1B1 in cardiovascular and cancer cells, possibly via activating the Aryl hydrocarbon Receptor (AhR), ROS generation, and inflammatory cytokines." (PMID 33185690, 2020). "The detrimental role of CYP1B1 in the pathogenesis of cancer and cardiovascular diseases, among other pathologies, has stimulated active research programs to identify and synthesize potent and selective CYP1B1 inhibitors." (PMID 33185690, 2020). "Overexpression of CYP1B1 has been observed in various cancer cell types that modify the biotransformation of chemotherapeutics, such as mitoxantrone, flutamide, docetaxel, and paclitaxel." (PMID 32370233, 2020). "The discovery in cancer cells of the overexpression of exogenous metabolizing P450s, such as CYP1B1, has increased interest in the creation of chemoprevention inhibitors and prodrugs intended to be triggered by P450s in cancer cells only." (PMID 31998435, 2020). "It is particularly important because CYP1B1 is overexpressed in a variety of cancers, such as prostate, breast, ovarian, colon and bladder cancer." (PMID 32726968, 2020). "A large number of phytochemicals with CYP1B1 inhibitory activity have been tested in clinical trials in healthy individuals, cancer patients, and patients with cardiovascular diseases." (PMID 33185690, 2020). "In cancer cells, CYP1B1 is thought to play a role in the bioactivation of xenobiotics, metabolism of steroid hormones, and the production of multiple pro-inflammatory and pro-angiogenic factors." (PMID 33185690, 2020). "The core dynamic DEGs (Mnda, Cyp1b1, Comp, Phex, Mmp3, Tnfrsf1b, Fbln5, and Nfkb2) had been reported to be closely related to the development and metastasis in tumor and cancer progress." (PMID 33042984, 2020). "CYP1B1 is an extrahepatic enzyme that is expressed in cardiovascular tissues and overexpressed in different types of cancers." (PMID 33185690, 2020). "Then, we will summarize the existing literature showing how CYP1B1 is involved in the cardiovascular toxicity of different cancer treatments and the potential cardiovascular protective effects of CYP1B1 inhibitors." (PMID 33185690, 2020). "Emerging evidence has demonstrated the potential association between gene polymorphisms and cancer risk, particularly in the CYP1 family including CYP1A1 and CYP1B1." (PMID 30765615, 2019). "Overexpression of CYP1A1 and CYP1B1 were reported in various types of cancer cells including breast cancer." (PMID 30728391, 2019). "The Specificity Protein 1 (SP1) transcription factor has been shown to contribute to the CYP1B1 mediated increase of growth regulatory genes like cyclin D1 as well as the proliferation, migration and invasion of cancer cells." (PMID 31370872, 2019).
cancer (continued). "3,4,5,4′-Tetramethoxystilbene is found to be a strong inhibitor of human cytochrome P450 1B1 (CYP1B1) that is overexpressed in a variety of hormone-dependent human cancers." (PMID 30893846, 2019). "The roles of PPARs have been investigated in cancer and fatty-acid metabolism, as well as in various CYP1B1-related tumorigenic states." (PMID 31775380, 2019). "The ERE (−84/49), activator protein 1 (−149/−129), and SP-1/XRE (−853/−824) transcription factor-binding sites in the human CYP1B1 promoter are important for regulating the transcription of CYP1B1 in cancer cells." (PMID 31775380, 2019). "It is thus apparent that CYP1B1 can lead to cancer by activating various compounds into carcinogenic forms and of interest are genetic polymorphisms that can alter enzyme levels." (PMID 30133114, 2018). "Multidrug resistance caused by an efficient metabolism of chemotherapeutics catalyzed by CYP1A1 and CYP1B1 is a crucial problem in cancer chemotherapy." (PMID 30147715, 2018). "Relative expression of CYP1B1 protein and mRNA was amplified in all the examined cancer cell lines compared with the RWPE-1 cells." (PMID 28388569, 2017). "CpG methylation of the promoter/enhancer has been suggested as a mechanism controlling cancer-specific expression of CYP1B1." (PMID 28388569, 2017). "Further, CYP1B1 SNPs have been concerned with the occurrence of various types of cancer, including lung, breast, endometrium, prostate, bladder, liver, cervix, and colorectum." (PMID 28377924, 2017). "Cytochrome P450 1B1 (CYP1B1) is recognized as a universal tumor biomarker and a feasible therapeutic target due to its specific overexpression in cancer tissues." (PMID 28388569, 2017). "Recently, several molecular targets of CYP1B1 have been found and indicate the participation of CYP1B1 in multiple pathways during the progression of various types of cancer." (PMID 28388569, 2017). "Studies have shown that CYP1B1 plays an important role in the initiation and promotion of cancer and, therefore, represents an attractive target for cancer chemoprevention." (PMID 28125044, 2017). "Previous investigations have suggested that an increased expression of CYP1B1 leads to its enhanced enzymatic activity in cancer cells." (PMID 29290975, 2017). "CYP1B1 protein is found in the cancer cells of various cancerous tissues but is undetectable or minimally expressed in the adjacent normal cells of cancer tissues and normal tissues." (PMID 28388569, 2017). "Because of demonstrated unequivocal involvement in smoking-induced cancer in laboratory animals, four candidate genes––AHR, CYP1A1, CYP1A2, and CYP1B1––were selected for a clinical genotype-phenotype association study of HNSCC risk in smokers." (PMID 27894333, 2016). "In the present study, we explored the role of CYP1B1 in carcinogenesis and cancer progression including the molecular mechanism that drives CYP1B1-mediated oncogenesis." (PMID 26981862, 2016). "Since CYP1B1 is implicated as a significant factor in the development of various cancers, a more detailed understanding of the precise mechanisms underpinning CYP1B1-mediated cancer progression may facilitate the development of new strategies for cancer treatment." (PMID 26981862, 2016). "To do so, we measured multiple hallmarks of cancer progression including cell proliferation, invasion, and migration following CYP1B1 induction or inhibition." (PMID 26981862, 2016). "Immunohistochemical staining was used to assess CYP1B1 expression in a panel of ovarian samples (53 primary cancer samples, 14 samples of metastastic cancer, 30 benign tumor samples and 19 normal tissue samples)." (PMID 25516145, 2015). "Among these enzymes, CYP1B1 has been shown to have 92% positive immunoreactivity in 172 OCs equally distributed in both primary cancer foci and also metastatic tissue." (PMID 25516145, 2015). "CYP1B1 protein is found in cancer cells but is undetectable in the normal cells of cancerous and normal tissues." (PMID 25860934, 2015).